IL6 (interleukin 6)
Diseases named in the same sentence as IL6 in open-access papers (continued):
Sharing a sentence is not in itself a finding about the gene and the disease.
Obesity (continued). "In obesity, the white adipose tissue produces large numbers of inflammatory agents including TNF-α and IL-6, which can affect the physiology of the adipose tissue locally, but also may induce systemic effects on the other organs." (PMID 32555600, 2020). "Also, significant increase in levels of IL-6 and IL-12 among class I and class III obesity groups with respect to normal control were detected." (PMID 32893859, 2020). "Moreover, in this obesity model, CARD9 deletion reduced IL-6 and IL-1β levels in plasma as well as pro-inflammatory cytokine secretion from isolated peritoneal cells." (PMID 30867470, 2019). "In patients with obesity and diabetes there was approximately 1.3-fold higher protein expression of leptin, and ~ 1.7-fold higher protein expression of IL-6 in SAT, as compared to non-obese controls." (PMID 31533725, 2019). "It is well-known that the post-exercise rise of circulating IL-6 is supported by SKM but contrarily, chronically slightly elevated blood IL-6 are found in metabolic conditions such as metabolic syndrome and insulin resistance, obesity, and T2DM." (PMID 30792697, 2019). "In this study, we were unable to determine circulating IL-6 levels in patients with normal-weight; thus a comparison between persons with obesity was not possible in this study." (PMID 31590286, 2019). "However, against the background of obesity and the progression of coronary atherosclerosis, the phenotype of EAT adipocytes from brown to white changes due to activation of the IL-6 signaling pathway of JAK-STAT3." (PMID 31173592, 2019). "A meta-analysis of the influence of adipokine polymorphisms in adipokine genes (LEP, ADIPOQ, IL-1β, IL-6, and TNF-α) in obesity susceptibility showed that there was not association with the risk of obesity and LEP variants in adults." (PMID 31354816, 2019). "Additionally, the excessive fat in obesity, especially visceral fat, produces cytokines including MCP-1, IL-6, and TNF-α, and adipokines such as leptin, which regulate pro-inflammatory cytokines." (PMID 31123488, 2019). "Classical obesity-induced pro-inflammatory cytokines, which mainly originate from immune cells and include TNF-α, IL-6, and TGF-β, participate in tumor cell proliferation and invasion, and may subsequently contribute to tumor progression." (PMID 31379820, 2019). "In particular, pro-inflammatory macrophage accumulation in adipose tissue is an important feature of obesity, correlating with local expression of inflammatory markers including tumor necrosis factor-α (TNF-α), interleukin-6 (IL-6), interleukin-1β (IL-1β) and C-C Motif Chemokine Ligand 2 (CCL2)." (PMID 31443599, 2019). "IL-6 promoter methylation in adipose tissue has not been investigated with regards to obesity, but in humans IL-6 promoter methylation has been investigated in circulating white blood cells with differing results." (PMID 30728429, 2019). "In obesity, it has been found that a shift in the activation state of macrophages in AT from M2Ф in lean animals to M1Ф, upon the activation of MФ, secretes numerous cytokines and chemokines, such as TNF-α, IL-1, IL-6 and chemokine MCP-1." (PMID 31357412, 2019). "IL-6 and IFN-γ play a crucial role in the ability of mast cells to regulate metabolism, and they may mediate diet-induced obesity and diabetes." (PMID 32063863, 2019). "This study focused on adolescents aimed to investigate early changes in obesity-related cardiac dysfunction, and to explore the correlations between indices of cardiac dysfunction and serum biomarkers, including hs-CRP, TNF-α, interleukin-6, M30 monoclonal antibody, and insulin resistance." (PMID 31120986, 2019). "Metabolic disorder and inflammation cause IR and promote leukocytes to secrete proinflammatory cytokines, including IL-6 and tumor necrosis factor-α (TNF-α), which provides a framework to understand how physiological stress, obesity, and diet promote IR." (PMID 31258478, 2019).
Obesity (continued). "Obesity can promote adipocytes to secrete pro-inflammatory factors, such as TNF-α, IL-6, and IL-18." (PMID 31440472, 2019). "High secretion of tumor necrosis factor-alpha (TNF-α), interleukin-6 (IL-6), monocyte chemoattractant protein-1 (MCP-1), and additional products of macrophages by adipose tissue with low sensitivity to insulin has also been detected in obesity." (PMID 30678306, 2019). "AT macrophages (ATM), which can account for up to 50% of the cellular content in the obese AT, are the primary source of pro-inflammatory cytokines (e.g., IL-6, TNF-α, IL1-β), and have been shown to be centrally important in obesity-related metabolic dysfunction." (PMID 31277269, 2019). "Moreover, in the experimental setting of obesity, a 1-h infusion of propofol resulted in increased airway resistance, atelectasis, and pulmonary inflammation mediated by increased TNF-α and IL-6 in lung tissue, with depletion of antioxidative enzymes." (PMID 31138279, 2019). "In the WAT, the obesity-induced chronic low-grade inflammation leads to the production and release of cytokines, such as monocyte chemoattractant protein-1 (MCP-1), interleukin-6 (IL-6) and tumor necrosis factor α (TNF-α)." (PMID 31426291, 2019). "The increased IL-6 levels previously observed in PCOS seem to be related to obesity and not to PCOS itself." (PMID 30595838, 2018). "Besides beneficial effects, chronic activation of STAT3 in obesity leads to constant expression of its own inhibitor, SOCS3, disrupting the homeostasis of the IL-6 signaling pathway." (PMID 30591653, 2018). "Nevertheless, in our child population with systemic low-grade inflammation, as in studies in children with obesity or type 1 diabetes, single bout exercise is not followed by increased IL-6 levels." (PMID 30008613, 2018). "At this relatively early stage of obesity, however, there was no detectable increase in protein concentrations of inflammatory cytokines in the extracellular fluid of BM including IL-1b, interleukin 6 (IL-6) or tumor necrosis factor (TNF)." (PMID 29453396, 2018). "Although all mechanisms underlying the link between obesity and IR are not entirely clear, it is known that hormones and cytokines such as resistin, tumor necrosis factor (TNF-α), and interleukin-6 (IL-6) secreted by adipocytes unbalance the action of insulin." (PMID 30513771, 2018). "Evidence shows that obesity results in chronic low-grade inflammation, which may elevate CRP levels due to the adipose tissues releasing IL-6 and TNF-α and inducing the synthesis of CRP by the liver." (PMID 30065944, 2018). "IL-6 stimulates lipolysis and fat oxidation in adipocytes, downregulates TLR4-induced TNF-α, IL-8, and macrophage metalloproteinase-1 (MCP-1) production by resident macrophages, and prevents mature onset obesity and insulin resistance in mice." (PMID 30534586, 2018). "Obesity promotes a low-intensity inflammatory state, leading to the over-secretion of inflammation mediators such as the tumor necrosis factor (TNF) and interleukin-6 (IL-6), which significantly affect endothelium function and homeostasis." (PMID 30400570, 2018). "Higher levels of IL-6 are produced by subcutaneous rather than visceral adipose tissue, although obesity results in increased visceral IL-6 levels." (PMID 29562620, 2018). "During obesity, immune cells obtain pro-inflammatory characteristics, and recruited macrophages are polarized to secrete pro-inflammatory cytokines including TNF and IL-6." (PMID 30096208, 2018). "Furthermore, IL-6 and TNF-α promoted the inflammatory phenotype of adipocytes, providing a link between low-grade inflammation, obesity, insulin resistance, and T2D." (PMID 30524198, 2018). "According to the literature, the adipose tissue in obesity is characterized by increased production and secretion of inflammatory molecules, such as TNF-α and IL-6, which may have local and systemic effects." (PMID 30020947, 2018).
Obesity (continued). "But the main source of IL-6 and TNF-α in obesity patients is not only from WAT." (PMID 30013512, 2018). "Since both obesity and T2DM are pro-inflammatory states, we examined the expression of several M1 phenotype markers in PBMC of lean, obese, T2DM, and T2DM on Metformin, including CD86, CD11c, CD169, IL-6, TNFα, iNOS, and CD36." (PMID 30356719, 2018). "Obesity may counteract this compensatory mechanism because the raised levels of TNF-α and IL-6 in obesity suppress ADIPO production by adipose tissue." (PMID 28947858, 2017). "Collectively, these results also suggest that IL-6+ Th17 cells and IFN-γ+ T cells are important causes of non-obese T2D and obesity-induced T2D, respectively." (PMID 28061846, 2017). "They concluded that mature 9-month old mice showed signs of dyslipidemia, impaired glucose tolerance and obesity possibly due to the lack of IL-6-induced activation of AMPK." (PMID 28579962, 2017). "IL-6 is another cytokine, similar to TNF-α, overexpressed in the adipose tissue in obesity." (PMID 28182687, 2017). "In summary, the present study showed that obesity created a low-grade chronic inflammatory microenvironment in the mammary tissue of women, as indicated by the elevations of several inflammatory cytokines, including TNF-α, IL-6, and IL-1β." (PMID 28402277, 2017). "The other suggested that higher IL-6 in MDD patients may be explained, at least in part, by obesity." (PMID 29176959, 2017). "During these obesity-related inflammatory responses, several inflammatory mediators such as tumor necrosis factor-α (TNF-α), monocyte chemoattractant protein-1 (MCP-1), and interleukin-6 (IL-6) are generally involved." (PMID 29081799, 2017). "In experimental models, it has been reported that obesity and excessive nutrition alters the inflammatory response, with increasing concentrations in TNF- α, IL1b, and IL-6, among others, resulting in the development of insulin resistance and excessive fetal growth." (PMID 28749954, 2017). "Similarly, high concentrations of IL-6 and TNF-α have been reported in the metabolic states of sarcopenia, obesity, and SO." (PMID 28677652, 2017). "Obesity and adipogenesis could increase production and secretion of proinflammatory cytokines such as TNF‐α, IL‐1β, and IL‐6 from macrophages into adipose tissues." (PMID 28572933, 2017). "It was observed that deletion of CERK suppressed high-fat diet obesity-mediated inflammatory cytokines IL-6 and TNFα and showed normal insulin signaling in an animal model." (PMID 29269995, 2017). "Furthermore, a strong link exists between obesity and altered glucose metabolism, and pro-inflammatory markers such as C-reactive protein (CRP), interleukin-6 (IL-6) and tumour necrosis factor alpha (TNF-α)." (PMID 28193219, 2017). "Thus, more rigorous and longitudinal studies in humans are needed to establish the sex-IL-6 relationship in patients with MDD and/or obesity." (PMID 29176959, 2017). "Both TNF and IL-6 are correlated with the body mass index (BMI), and TNF is known to play a role in obesity and in particular in the insulin resistance and diabetes that often accompany obesity." (PMID 27148273, 2016). "Obesity is characterized by the expression of elevated levels of proinflammatory cytokines and chemokines like TNF-α, IL-1, IL-6, and MCP-1, and these factors have adverse effects on the differentiation and activation of osteoblasts while having supportive effects on osteoclasts." (PMID 27746742, 2016). "Recently, the obesity has been considered a physiological state of chronic inflammation, characterized by elevated levels of inflammatory markers including C-reactive protein (CRP), interleukin-6 (IL-6), and tumor necrosis factor alpha (TNF-α)." (PMID 27899895, 2016). "Thus, while IL-6-dependent signaling plays a role in diethylnitrosamine (DEN)-induced HCC in lean mice, obesity is more likely to promote hepatocarcinogenesis by a different mechanism." (PMID 30873458, 2016).
Obesity (continued). "Thus, adipocyte exposure to gACRP promoted a shift towards an anti-inflammatory profile reducing the release of inflammatory cytokines upregulated in obesity and contributing to insulin resistance, such as MCP-1, IL-6, or IL-8." (PMID 25629558, 2015). "The IL6, LEPR, NAMPT, and AMD1 gene variants previously found to associate among Indian children did not associate with risk of obesity or obesity-related quantitative measures among Caucasian children and juvenile men from Denmark." (PMID 26558825, 2015). "In addition, IL‐6, a factor released from exercise trained muscle, enhances the release of GLP‐1 by the intestine which contributes to improved glycemia under obesity and diabetes." (PMID 25602012, 2015). "Specifically in this setting, IL-6 has biological roles including induction of lipolysis and suppression of TNF production, in contrast to the negative effects of IL-6 in obesity and adipose tissue." (PMID 26549941, 2015). "Unlike “classic” pro-inflammatory mediators, for example TNF-α, IL-6 and C-reactive protein, T cell-derived cytokines, such as IL-17A, have not been extensively investigated in obesity." (PMID 26263971, 2015). "The observation that GM3 treatment of 3T3-L1 adipocytes induces a fourfold increase in IL-6, PAI-1 and TNF-α mRNA suggests that gene expression of proteins involved in obesity induced thrombosis and inflammation may be dependent on its abundance." (PMID 26102277, 2015). "Previous models of diet-induced and genetic obesity has shown that adipose tissue presents an important source of pro-inflammatory adipocytokines, such as tumor necrosis factor α (TNF-α), interleukin-1 (IL-1), and interleukin-6 (IL-6) during weight gain." (PMID 26247966, 2015). "Generally, expansion of adipose tissue in obesity leads to increased macrophage infiltration and inflammation with enhanced production of proinflammatory cytokines such as tumor necrosis factor α (TNF-α) and interleukin 6 (IL-6)." (PMID 25816341, 2015). "Adipocytes and infiltrating inflammatory cells (primarily macrophages) present within the tissue secrete key inflammatory proteins, such as TNF-a, IL-6, and CCL2/monocyte chemoattractant protein, and their gene expression and release are markedly increased in obesity." (PMID 25887648, 2015). "The current study illustrates that four variants (IL6 rs2069845, LEPR rs1137100, NAMPT rs3801266, and AMD1 rs2796749) implicated in childhood obesity among Indians are not strongly associated with obesity among Danish children and juveniles." (PMID 26558825, 2015). "Furthermore obesity as well as STEMI is considered a low-grade inflammatory state, as demonstrated by increased levels of the pro-inflammatory cytokines interleukin-6 and tumor necrosis factor-alpha, and acute phase proteins such as C-reactive protein." (PMID 26162888, 2015). "Systemic measures of cytokines and hormones were not significantly different except for obesity-induced increases in Il-6." (PMID 25354395, 2014). "Moreover, we also found that the immature ATDCs expressed higher levels of IL-6, TGF-β and IL-23, resulting in the enhancement of Th17 cells response, and then prompt diet-induced obesity adipose tissue inflammation." (PMID 24642966, 2014). "Using contact cocultured adipocytes/macrophages system and mimicking the inflamed adipose tissue environment in obesity, we first found that the HO-1 induction by hemin significantly reduced levels of inflammatory cytokine (TNF-α and IL-6) release from the cocultures." (PMID 25477711, 2014). "In conclusion, our results show that the HP2/HP2 genotype is associated with elevated TNF-α and IL-6, but not with hsCRP, levels in obese subjects, suggesting that the functional differences of HP subtypes could be associated with different outcomes of obesity." (PMID 24868113, 2014).
Obesity (continued). "Therefore the aim of this study was to evaluate associations between inflammatory markers or cytokines such as IL-6, TNF-α and hsCRP, and both classical and newer obesity parameters and indices in obese normo- and hypertensive subjects." (PMID 24507240, 2014). "In the MSG-treated mice model, we found that obesity induced a low-grade chronic inflammatory state accompanied by pro-inflammatory cytokine (TNF-α and IL-6) increments, with adiponectin gene expression reduction and plasma adiponectin elevation following weight loss." (PMID 24979131, 2014). "The results indicated that obesity promoted IL-6 production, but did not amend spontaneously due to TNFα deficiency." (PMID 24522555, 2014). "Earlier studies have also revealed that both IL-6 and TNF increase hepatic production of C-reactive protein (CRP), a major acute phase protein, which is a nonspecific but sensitive marker of infection and tissue inflammation that is increased in obesity." (PMID 24877058, 2014). "Our results demonstrate only an 1.5-fold increase in IL-6 levels in patients with CLBP, which could even occur after physical activity or in obesity." (PMID 25122126, 2014). "Their results support the notion that obesity promotes hepatic tumors through induction of TNFα and IL-6, even under conditions in which DEN administration does not induce HCC on its own." (PMID 25533006, 2014). "Unlike previous reports of obesity augmenting the inflammatory response, we found that the IL-6 inflammatory response was muted in overweight and obese patients compared with those with a BMI of less than 25 kg/m2 in early septic shock." (PMID 23786836, 2013). "Notably, obese LFD-derived IL-1RI−/− adipose explants secreted negligible levels of IL-6, demonstrating the necessity of a HFD insult to drive the localized inflammation of obesity." (PMID 23921145, 2013). "Preliminary results from our laboratory have recently identified a number of interactions between three IL-6 SNPs (IL-6 –174 G > C, IVS3 +281 G > T, and IVS4 +869 A > G) and dietary fatty acids on obesity and serum lipid levels in both black and white SA women." (PMID 23698162, 2013). "Additionally, we discuss a working biological model on the onset of destructive periodontal disease in individuals with obesity or metabolic syndrome based on elevated levels of tumor necrosis factor-α (TNF-α) and interleukin 6 (IL-6) in these conditions." (PMID 24068858, 2013). "Moreover, high IL-6 expression and the activation of IL-6 signaling pathway lead to HCC development in obese mice, representing a link between obesity and HCC." (PMID 23533994, 2013). "Obesity is considered as an inflammatory status, because proinflammatory molecules, expressed by adipose tissue such as leptin, TNF-α, IL-6, TGF- β1, adiponectin and C-reactive protein, are increased in obese subjects, especially in females (mainly C-reactive protein and leptin)." (PMID 24028436, 2013). "In conclusion, we have demonstrated in a population-based study that high waist circumference, and raised serum levels of the pro-inflammatory adipokines, IL-6 and TNFR2, can predict the development of cancers in a Chinese cohort with relatively low obesity prevalence." (PMID 24205276, 2013). "This hypothesis is in agreement with previous data from our group showing that visceral fat contributes to increased plasma IL-6 and CRP in obesity." (PMID 23984354, 2013). "In conditions of hyperleptinemia, as occurs in obesity, an expansion of the Th1 cells in the adipose tissue and an increase in pro-inflammatory cytokine secretion (as TNF-α, IL6 and IL12) have been described together with an increase of CD8+ T cells, macrophages and mast cells." (PMID 24084730, 2013). "As for IL-6, a cytokine known to be involved in the development of obesity complications, it is possible that the observed lack of effect is due to the fact that IL-6 soluble receptor was not added to IL-6 in our experiments." (PMID 23460908, 2013).